INS (insulin)
Diseases named in the same sentence as INS in open-access papers (continued):
Sharing a sentence is not in itself a finding about the gene and the disease.
Insulin resistance (continued). "Insulin resistance is defined by compensatory hyperinsulinemia due to a decreased sensitivity of target tissues, such as skeletal muscles, the liver, and adipose tissue, to insulin." (PMID 38069300, 2023). "Intrauterine growth restriction can affect foetal insulin secretion, and insulin resistance trends in PCOS may be involved in developmental origin and preprogramming as a nutritional compensation mechanism." (PMID 36631836, 2023). "In addition, in some insulin-related knockout mouse models, in which insulin resistance is induced in one or more tissues, a significant increase in the lifespan of mice can be observed." (PMID 37408986, 2023). "Obesity and weight gain are linked to PCOS by the effects of weight gain on insulin resistance and hyperinsulinemia, as well as the dysmetabolic and steroidogenic effects of impaired PI3-kinase and intact MAP kinase post-receptor insulin pathways, respectively." (PMID 37374308, 2023). "Interestingly, the global rise in AD parallels trends in insulin resistance and metabolic syndrome, hinting at an important relationship between peripheral insulin and brain function." (PMID 38068958, 2023). "Insulin resistance is a condition characterized by a relative inability of target tissues to respond to insulin action due to the downregulation of insulin receptor (IR) expression, its inability to bind insulin, or faulty activation of the insulin signalling cascade." (PMID 36671568, 2023). "Recent evidence suggests a link between mitochondrial ceramides and insulin sensitivity, with the observation that reducing mitochondrial, but not global, ceramide in the liver protects against the development of diet-induced insulin resistance and obesity." (PMID 38149844, 2023). "Furthermore, an increase in growth hormone (GH) and a decrease in insulin (Ins) attended by insulin resistance (InsR) and reduced IGF-1 concentrations occur, which together are highly likely to determine the observed metabolic adaptation." (PMID 37835703, 2023). "These phenotypic changes were not caused by severe insulin resistance in Trpm7R/R mice, because insulin tolerance was comparable in both genotypes." (PMID 36574297, 2023). "Indeed, our results indicate that senescent myoblasts showed signs of insulin resistance as they lost the ability to phosphorylate Akt2 in response to insulin." (PMID 36797255, 2023). "Furthermore, our findings are also in line with a recent meta-analysis of patients with type II diabetes that showed similar effects of LL-RT and HL-RT when compared with AT on glycated hemoglobin, insulin levels and insulin resistance." (PMID 36918949, 2023). "In our study, these changes were significantly reversed after AAL intervention, which indicates that AAL could improve hyperglycemia and insulin resistance, enhance insulin sensitivity, and accelerate glucose metabolism." (PMID 37836402, 2023). "In addition, the HFD enlargement in blood glucose and insulin content were reversed by herpetrione administration; simultaneously, herpetrione decreased the homeostasis model assessment of insulin resistance (HOMA-IR) index." (PMID 38034083, 2023). "They potentially help the metabolic control of T2DM through increased satiety (decreased food intake), improved insulin sensitivity and insulin resistance, increased glucose tolerance, an altered gut hormone response, changed gut microbiota and enhanced body fat reduction." (PMID 37511996, 2023). "A prevailing hypothesis suggests that insulin resistance results from impaired proximal insulin signalling, leading to reduced Akt activation." (PMID 37248992, 2023). "SOCS3 inhibits insulin signaling and leads to the development of insulin resistance." (PMID 36609306, 2023).
Insulin resistance (continued). "Our findings also extend the scientific literature on the role of these metabolites in the etiology of insulin resistance and impaired insulin secretion and highlight the need for additional comprehensive metabolomic studies in well-characterized multiethnic cohorts." (PMID 37005925, 2023). "Various parameters were measured, including fasting blood glucose, fasting insulin, homeostasis model assessment of insulin resistance (HOMA-IR), triglyceride and glucose (TyG) index, lipid profile, alkaline phosphatase (ALP), osteocalcin, and 25(OH)-Vitamin D levels." (PMID 38333723, 2023). "Rats with MASLD developed insulin resistance, showing increased fasting blood glucose and insulin levels, increased weight of epididymal fat, obvious hepatic steatosis and inflammation and down-regulated IRS-2 mRNA and protein levels compared with normal controls." (PMID 37895151, 2023). "Further studies must be conducted evaluating both insulin levels and insulin resistance." (PMID 37960202, 2023). "The development of insulin resistance may also be influenced by inadequate oxidative capacity, and data suggests that higher CRF is associated with improved insulin dynamics due to enhanced mitochondrial flexibility." (PMID 37048823, 2023). "Impaired OXPHOS and mitochondrial dysfunction may contribute to insulin resistance (IR) by disrupting insulin signaling pathways and impairing glucose metabolism." (PMID 37762427, 2023). "Weight gain and increased fat may persist throughout adulthood among women with early menarche, which correlates with impaired insulin response, increased insulin resistance, and dyslipidemia, eventually resulting in a range of metabolic issues." (PMID 37286578, 2023). "Next, we measured fasting glucose and insulin levels and estimated insulin sensitivity using the insulin resistance index (HOMA-IR), calculated using the University of Oxford HOMA calculator software as: [fasting glucose (mmol/L) × fasting insulin (μIU/mL)] ÷ 22.5." (PMID 37006244, 2023). "Moreover, researchers have shown that insulin resistance in T1DM rats is associated with triglyceride accumulation in skeletal muscle, as shown by insulin tolerance tests." (PMID 37065747, 2023). "Furthermore, leptin and CRP increase insulin resistance whereas adiponectin improves insulin sensitivity; primary features of GDM." (PMID 36520252, 2023). "An elevated insulin level is an indirect sign of insulin resistance." (PMID 36832300, 2023). "DM is classified into two major types: type 1 (T1) DM, an autoimmune disorder that destroys pancreatic beta cells leading to insulin dependency, and type 2 (T2) DM, a complex metabolic disorder driven by insulin resistance (IR) and insufficient insulin production." (PMID 38003446, 2023). "Although Ehmt2K182R/K182R mice had worsened insulin sensitivity compared to WT mice upon Dex treatment, overexpression of Irs2 in the liver of Ehmt2K182R/K182R mice significantly ameliorated glucose intolerance and insulin resistance in Dex-treated mice." (PMID 37253782, 2023). "Insulin resistance (IR) is characterized by reduced sensitivity to the effects of insulin." (PMID 37993902, 2023). "Normal cells may overcome insulin resistance by producing more insulin or by having more cells, but insufficient compensation leads to glucose intolerance." (PMID 37954695, 2023). "According to these findings, our preliminary results demonstrated that Prdx6−/− mice subjected to hindlimb unloading (HU) displayed disrupted glucose homeostasis, characterized by an increase in glucose and insulin secretion levels, suggesting the presence of insulin resistance." (PMID 38137846, 2023). "There is a negative correlation between Vit B12 and HOMA-IR and in addition to this, FEV1: FVC% correlates negatively with BMI (0.53), WHR (0.50), glucose (0.68), insulin (0.68), Insulin resistance (0.80), and a positive correlation between FEV1: FVC% and Vit B12 (0.73)." (PMID 37362491, 2023).
Insulin resistance (continued). "In the diabetic mice, isoquercitrin could significantly improve the sensitivity of adipose tissue to insulin and attenuate insulin resistance." (PMID 37293505, 2023). "Furthermore, insulin-induced anti-aggregation observed in subjects with normal BMI is blocked in patients with obesity-related insulin resistance, indicating that obesity is closely related to platelet activity abnormalities." (PMID 37686837, 2023). "These agents may reduce insulin resistance and increase insulin secretion and glucose absorption from blood." (PMID 36902218, 2023). "Insulin resistance (IR) is a general term used to describe impaired insulin-mediated glucose uptake in adipose tissue, skeletal muscle, liver and pancreas, and has been regarded as a predictor for adverse outcomes in patients after myocardial revascularization." (PMID 37649025, 2023). "Interestingly, autophagy was found to affect insulin signaling such that hepatic autophagy impairment promoted obesity and induced insulin resistance." (PMID 37876013, 2023). "At first, increased insulin production compensates for insulin resistance." (PMID 38104079, 2023). "Children with JIA and a BMI lower than 23 kg/m2 had lower serum leptin than healthy subjects, while children who were overweight or obese had higher prevalence of insulin resistance, lower insulin sensitivity and higher insulin secretion than age matched overweight or obese healthy children." (PMID 37441710, 2023). "Overcoming insulin resistance in PCOS at the level of key insulin target tissues such as skeletal muscle would suppress compensatory hyperinsulinemia and thus indirectly reduce insulin-stimulated androgens overproduction and their bioavailability, thereby improving androgen levels in PCOS." (PMID 37371678, 2023). "If this is the case, targeting a single kinase or pathway may only confer a partial benefit to insulin sensitivity, pointing towards the benefits of a polypharmacological approach in drug discovery for insulin resistance." (PMID 36808134, 2023). "Insulin resistance of the patients was evaluated according to the fasting insulin (HOMA) index." (PMID 36829146, 2023). "We conclude that treating NAFLD with VLCKD is both beneficial and safe, which is possibly thanks to the simultaneous effects of different factors, such as the reduction of insulin levels, insulin resistance, body weight and fat mass, and the induction of ketosis." (PMID 36839183, 2023). "Thus, overexpression of EHMT2 prevents palmitic acid- or glucosamine-induced insulin resistance by preserving normal insulin signaling." (PMID 37253782, 2023). "Insulin resistance and/or insulin secretion impairment usually occurs in T2DM patients." (PMID 38223574, 2023). "In addition, the triterpenes favored the translocation of GLUT-4 to the cell surface of insulin-resistant cells, increased AMPK activation and PTP-1B inhibition, improving the effects caused by insulin resistance." (PMID 37432178, 2023). "designed a metformin-versus-placebo randomized clinical trial involving 15 women with insulin resistance and low milk production despite regular breast emptying; their hypothesis was that an intervention targeting insulin action could improve milk production." (PMID 37409227, 2023). "Insulin-mediated activation of Akt is central to glucose disposal in mammals and insulin-stimulated Akt phosphorylation is decreased in the skeletal muscle of individuals with insulin resistance." (PMID 36894534, 2023). "Similarly, we found correlations between HOMA-IR and the VAI, LAP, and TyG indices, all of which represent insulin-free metabolic determinants of insulin resistance." (PMID 38068348, 2023). "POM121C may contribute to insulin resistance in type 2 diabetes by stimulating adipogenesis and increasing the sensitivity of adipocytes to insulin." (PMID 37569434, 2023).
Insulin resistance (continued). "Furthermore, a recent study reported that insulin therapy in T2DM is associated with an increased risk of carotid atherosclerotic lesions, which is partly attributable to higher insulin resistance in patients receiving insulin therapy." (PMID 37528628, 2023). "Therefore, the regulation of both TNF-α and adiponectin and the regulation of proteins, involved in the insulin pathway, lead to the protection against insulin resistance." (PMID 36647430, 2023). "Importantly, development of insulin resistance in the periphery also extends to the brain, with mechanisms and consequences of dysregulated insulin signaling in specific regions largely under explored." (PMID 36979453, 2023). "Metformin was shown to display anti-cancer effects through its insulin-lowering activity, which may slow tumor proliferation in individuals with insulin resistance." (PMID 38146457, 2023). "Decreased insulin secretion and increased insulin resistance have also been suggested to this end." (PMID 37510992, 2023). "Indeed, liver and global deletion of ChREBP lead to glucose intolerance and insulin resistance in mice, while liver-specific ChREBP overexpression in mice fed a high-fat diet ameliorates insulin signaling despite increased hepatic lipid accumulation." (PMID 36923222, 2023). "Furthermore, the glucagon level, which is elevated in the presence of high insulin and insulin resistance state, is another main factor that regulates autophagy." (PMID 37876013, 2023). "A previous study reported that 4% egg white hydrolysates could significantly enhance insulin sensitivity in HFD-induced insulin-resistant rats." (PMID 37111032, 2023). "Moreover, we detected a negative correlation between AIP and vitamin D levels and a positive correlation with BMI, insulin resistance, and insulin levels." (PMID 37189890, 2023). "In addition, we aimed to measure the effect of COVID-19 on the non-insulin-based insulin resistance indexes, TyG, TyG-BMI, TG/HDL-C, and METS-IR, in elderly patients with type 2 diabetes." (PMID 36846644, 2023). "TZP might decrease the metabolic requirement for insulin release by pancreatic β-cells by diminishing insulin resistance in individuals with type 2 diabetes." (PMID 37779743, 2023). "As proven in in vitro and in animal models, mTOR-Is may decrease beta-cell mass through an increment of the rate of apoptosis, induce impairment of glucose-induced insulin secretion, and facilitate glucose intolerance and insulin resistance." (PMID 37250653, 2023). "The modulation of TT by probiotics may be linked to several mechanisms, including their capacity to reduce inflammation in the gut and ultimately reduce insulin levels and insulin resistance that stimulates testosterone secretion." (PMID 37972004, 2023). "The hypoglycemic mechanism of D. nobile may be related to the activation of the insulin signaling pathway, thus improving this disorder of glucose and lipid metabolism and insulin resistance." (PMID 36985655, 2023). "These pathways are closely related to the occurrence of insulin resistance, which is the main pathogenic factor of T2DM, manifesting in a decreasing insulin sensitivity of target tissues (liver, skeletal muscle, and fat), resulting in a decreased ability for glucose absorption." (PMID 37834276, 2023). "Another critical pathway altered with insulin resistance is insulin signaling." (PMID 38137341, 2023). "PTP1B, a negative regulator of the insulin signaling cascade that acts as an IR phosphatase, is upregulated by HFD in various tissues, including skeletal muscle, and is thought to be one of the causes of HFD-induced insulin resistance." (PMID 37389126, 2023). "LPL activity is enhanced by insulin and, on the contrary, attenuated by insulin resistance." (PMID 36979405, 2023).
Insulin resistance (continued). "In accordance with the present study, it has been shown that the administration of antioxidant vitamins (C and E) to DEHP-induced type-2 diabetic rats significantly reduced fasting serum insulin and insulin resistance, and facilitated insulin sensitivity in skeletal muscle." (PMID 38274944, 2023). "Therefore, TMD can improve glucose tolerance and insulin resistance, and among the various TMD types, HSLA was most effective in regulating glucose homeostasis by enhancing insulin sensitivity in estrogen-deficient rats." (PMID 37569228, 2023). "Insulin resistance could interfere with the distal effects of autocrine insulin secretion from the sperm and negatively affect capacitation." (PMID 38203349, 2023). "However, it is known that peripheral delivery of insulin, bypassing the normal hepatic extraction, results in abnormal insulin balance and promotes insulin resistance." (PMID 35524739, 2022). "Insulin resistance refers to the state where the efficacy of the insulin on target tissues becomes compromised particularly on adipocytes, hepatocytes and skeletal muscles which leads to hyperglycemia by impairing utilization of glucose and increasing hepatic glucose output." (PMID 35282429, 2022). "Depending on the presence of hepatic steatosis there were significant differences in the values of alanine aminotransferase (p=0.0006; R 0.25), glycaemia after 2 hours of OGTT (p=0.0059; R 0.20), fasting insulin (p= 0.0006; R 0.23) and all insulin resistance indices." (PMID 36387906, 2022). "Indeed, mice deficient in VAT Treg cells, while susceptible to obesity associated insulin resistance, are better protected from age-associated insulin resistance, suggesting a complexity of VAT Treg cell-mediated regulation of insulin metabolism." (PMID 35359918, 2022). "Its mechanism may be related to improving the sensitivity of peripheral target organs to insulin, reducing plasma insulin levels, increasing insulin sensitivity index and improving insulin resistance." (PMID 36091757, 2022). "They reported that the fasting insulin level could be used as an easy test to detect insulin resistance in patients with obesity." (PMID 35409375, 2022). "The pathogenesis of GDM in pregnant women with obesity is complex, with contribution of exaggerated insulin resistance, dyslipidaemia, reduced insulin secretion, increased inflammatory cytokines, and changes in amino acids, fatty acids, ketone bodies and adipokines." (PMID 36295825, 2022). "In animal models, C16 carbon chain ceramides have been reported to be involved in insulin signaling and may contribute to obesity and insulin resistance." (PMID 36551897, 2022). "One plausible explanation for this biphasic phenomenon is that long-term exposure to insulin could induce insulin resistance, thus deactivating the insulin signaling pathway." (PMID 35974022, 2022). "In addition to islet autoimmunity, LADA patients tend to be insulin resistant, and the degree of insulin resistance seems to depend on the degree autoimmunity, so that it is more pronounced in LADA patients with low levels of GADA." (PMID 35846274, 2022). "Fasting insulin levels and the HOMA-IR index indicate a risk for insulin resistance." (PMID 36447164, 2022). "However, the large number of ongoing RCTs using novel therapeutic agents targeting insulin secretion, insulin resistance, liver metabolism and other mechanisms that differ between the subgroups holds promise for precision healthcare." (PMID 34981134, 2022). "Insulin resistance (IR) is a condition in which the efficiency of insulin in promoting glucose uptake and utilization is reduced and in which the body compensates by producing too much insulin to maintain blood sugar stability, eventually leading to hyperinsulinemia." (PMID 36117320, 2022).